IRF7 (interferon regulatory factor 7)
Diseases named in the same sentence as IRF7 in open-access papers (continued):
Sharing a sentence is not in itself a finding about the gene and the disease.
viral infection (continued). "Our previous study demonstrated that AIP binds to IRF7 and this interaction is enhanced by virus infection." (PMID 38043800, 2023). "Several studies have shown that Irf7 is involved in the regulation of inflammation in various diseases, including autoimmune diseases, viral infections, and cancer." (PMID 37946128, 2023). "Inactive IRF7 present in the cytoplasm and viral infection triggers translocation into the nucleus to activate transcription." (PMID 36878637, 2023). "Positive feedback regulation of IRF7 contributes to the host’s regulation of interferon expression in the late stage of viral infection." (PMID 37446070, 2023). "TRIM28, the IRF7-specific SUMO E3 ligase, increased the SUMOylation of IRF7 during viral infections, inhibiting its transcriptional activity." (PMID 37638030, 2023). "For instance, Rand and colleagues reported cell-intrinsic stochasticity in the activation of IRF7 and NF-κB upon virus infection of murine cells." (PMID 37558422, 2023). "To determine the stage of HIV-1 life cycle during which IRF7 enhances viral infection, we measured reverse transcription (RT) products using a quantitative PCR (qPCR) assay." (PMID 37328105, 2023). "IRF7 is a transcription factor that serves as a crucial regulator of the type I IFN immune response to viral infections, including HSV." (PMID 37097753, 2023). "It is undeniable that IRF7 plays a key role in host defense against various bacterial and viral infections by promoting the production of IFN-I." (PMID 37251373, 2023). "In naïve animals, virus infection resulted in upregulation of IRF7/interferon responses in PVG, in contrast to BN, which lacked an IRF7/interferon signature and instead upregulated IL-25 and IL-33 expression." (PMID 36895568, 2023). "Our findings revealed new mechanisms by which SAMHD1 suppresses IFN-I induction through the MAVS, IKKε, and IRF7 signaling axis in the context of viral infection, which help better understand the role of SAMHD1 in innate immunity." (PMID 37328105, 2023). "As an interferon regulatory factor, IRF7 also plays a key role in host defense against bacterial, parasitic and viral infections." (PMID 37251373, 2023). "Given that AIP is inducibly phosphorylated during virus infection, we next assessed the interaction between IRF7 and the AIP T40 mutants by coimmunoprecipitation assays." (PMID 38043800, 2023). "IFN-γ-regulating genes (IRGs), including IRF7, were significantly upregulated in the oral mucosa following viral infection." (PMID 37047071, 2023). "The stark response to viral infection shown in the transcriptional increase of factors such as Ifitm2, Irf7, Stat1, and Eif2a, among others, indicates a heart actively mounting a host response to the invading SARS-CoV-2." (PMID 37081485, 2023). "Viperin can be induced by IRF-3 and IRF-7 mediated production of IFNs and combat different virus infection in myeloid DCs." (PMID 36315280, 2023). "IRF7 is a crucial regulator of IFN-I against viral infections and is activated by the signaling cascade response from recognizing pathogenic nucleic acids." (PMID 36537793, 2023). "2′-5′ oligoadenylate synthetase-like 1 (OASL1) deficient (Oasl1−/−) mice are resistant to viral infections, as OASL1 specifically inhibits the translation of interferon regulatory factor 7 (IRF7), the master transcription factor for interferon-1 (IFN-I)." (PMID 38333186, 2023). "IRF7 is normally localized in the cytoplasm, but upon virus infection IRF7 is phosphorylated, undergoes dimerization, and translocates into the nucleus where it induces the expression of type I IFN." (PMID 38043800, 2023). "Elevated expression of the decapping enzyme Dcp2 induced by viral infection and double-stranded RNA treatment inhibited IRF7 mRNA stability and protein accumulation." (PMID 37638030, 2023). "This, in turn, promotes protein degradation, while E3 Ub ligase Pellino 3 regulates TLR3 and viral infection-mediated IFN-I expression by targeting the IRF7 pathway." (PMID 37446070, 2023).
viral infection (continued). "IRF3 is critical for early induction of IFN expression in most cells post-viral infection; IRF7, which induces both IFNα and IFNβ expression, has functions in the antiviral activity of IFN in a later stage." (PMID 37090696, 2023). "Further, RUNX2 has been demonstrated to play a role in T-cell lymphoma, acute myeloid leukemia, and multiple myeloma and to facilitate the response to viral infection through the control of Interferon Regulatory Factor 7 (IRF7)." (PMID 35886938, 2022). "ORF45, as KSHV immediate early protein, blocks the phosphorylation and nuclear accumulation of IRF7 during viral infection." (PMID 36366509, 2022). "IRF7 has a particularly important role in pDCs, cells which produce IFNα in response to a viral infection or in a dysregulated manner which contributes to autoimmunity." (PMID 35013241, 2022). "Post‐translational regulations of IRF3 have profound impacts on host antiviral immunity, however, relatively little is known about the mechanism by which the biological function of IRF7 is modulated during viral infection." (PMID 35792897, 2022). "These kinases are considered master regulators of inflammation and innate immunity via control of the transcription factors IRF3, IRF7 and NF-κB during viral infection." (PMID 36311756, 2022). "Avian interferon regulatory factors 1 and 7 (IRF1 and IRF7) play important roles in the host’s innate immunity against viral infection." (PMID 35891486, 2022). "Given that IRF7 plays a predominant role in the late phase of viral infection, it is conceivable that NEURL3 preferentially regulates the activity of IRF7 rather than IRF3." (PMID 35792897, 2022). "By illuminating new avenues of investigation, therapeutic strategies targeting IRF7 or TBK-1 can be developed to boost vaccine responses to viral infections such as influenza and SARS-CoV-2 to alleviate substandard vaccine outcomes in the older population." (PMID 35849213, 2022). "In this context, it is possible that reduced levels of IFN regulatory factor IRF3 or defective IRF7 function reduces the level of IFNα/β gene expression, increasing the sensitivity to viral infection." (PMID 36443794, 2022). "IRF3 and IRF7 are the master transcription factors driving IFN production in response to viral infection." (PMID 36172355, 2022). "IRFs, especially IRF3 and IRF7, are members of the interferon regulatory factor family, which are closely related to the expression of interferon genes during virus infection." (PMID 35457287, 2022). "Plasmacytoid dendritic cells (pDC) have been characterized as major producers of rapid and high levels of type I IFNs in viral infection largely owing to their high constitutive levels of the transcription factor IRF7." (PMID 35163747, 2022). "IRF3 and IRF7 are two key transcription factors that modulate type I IFN expression upon viral infection." (PMID 35215986, 2022). "Knockdown of YAP/TAZ or TEADs increased the transcriptional expression of antiviral and proinflammatory factors IFNB1, CXCL8 and IRF7 induced by virus infection." (PMID 35503798, 2022). "Viral infection leads to IRF7 activation and translocation into the nucleus, where it binds to the promoter regions of interferon gene to activate the transcription." (PMID 36366509, 2022). "During viral infection, IRF7 expression was still repressed in KD/KO cells compared to WT cells particularly early on during the infection." (PMID 35085371, 2022). "IRF7 is a lymphoid-specific factor, which is constitutively expressed in the immune cell cytoplasm, and can also be induced by type I interferon, virus infection, and external stimuli in various cells." (PMID 34830083, 2021). "Another candidate by SNP rs7113204 is IRF7 (Interferon regulating factor 7) that is known to play a key role in the production of IFN-α in response to viral infections." (PMID 34781942, 2021).
viral infection (continued). "A previous study has revealed that a Cullin 1-based ubiquitin E3 ligase mediates ubiquitin-dependent protein turnover of IRF7 before and after viral infection in most cell types." (PMID 34506605, 2021). "TRIM28-mediated SUMOylation of IRF7 increases during viral infection, resulting in transcriptional repression." (PMID 34782737, 2021). "STAT1 and IRF7 are particularly important during virus infections because of their prominent role in regulating antiviral functions." (PMID 34653236, 2021). "The FoxO signalling pathway was determined to be an essential immune-modulatory cascade that was regulated by IRF7 as a functional host immune response to viral infection." (PMID 34102081, 2021). "The key gene module that divided acute cases into two groups was reconstructed employing prior knowledge and was centred on IRF7, a key regulator of interferon expression in response to viral infection." (PMID 34945765, 2021). "Here, expression of the intron-retained IRF7-isoform-dampened type I IFN response to single-stranded virus infection." (PMID 33572560, 2021). "The roles played by IRF7 are the viral infection-induced MHC class I upregulation and priming of the CD8 arm of acquired immunity, and not simply limited to the type I IFN response." (PMID 34389779, 2021). "We then evaluated IRF7 phosphorylation status and translocation in each IKKε isoform transfectant in the presence of ubiquitin to mimic virus infection conditions." (PMID 34079066, 2021). "It is well known that IRF7 partners with IRF3 to modulate the type I IFN response in mammalian viral infections." (PMID 34102081, 2021). "For example, IFN-α expression is completely abolished, and the expression of IFN-β is markedly inhibited in IRF7 knockout mice in response to viral infections." (PMID 32881988, 2020). "The signaling adaptor MyD88 has been demonstrated to activate IRF-7 for induction of type I IFN by pDCs in response to virus infection and TLR7/9 activation." (PMID 32373120, 2020). "The stimulation of the IRF-7 gene has been shown toprovide host defense against viral infection by inducing Viperin/RSAD2 and our data shows that Viperin/RSAD2 are highly up-regulated in cattle." (PMID 32325933, 2020). "IRF7 is activated upon virus infection, and it stimulates a set of genes involved in host anti-virus defenses." (PMID 32437400, 2020). "The type I IFN induction models from in vitro studies using mouse embryonic fibroblast or primary tracheal epithelial cells of Irf7-/- mice showed an abolished production of type I IFNs upon viral infection." (PMID 32252379, 2020). "Whilst IRF-3 is constitutively expressed in all cell types, IRF-7 is constitutively expressed only in plasmacytoid dendritic cells (pDCs), while in most of the other cell types it is expressed only after viral infection." (PMID 32373120, 2020). "The investigation on the mechanisms for the induction of IFNs showed that poly(dA:dT) treatment of the cells enhanced the phosphorylation of IRF3 and IRF7, the key and positive regulators of IFNs during viral infections." (PMID 33664729, 2020). "Taken together, the IFNβ-IRF7 forward feedback loop is a sentinel at the early stages of viral infection in local environments that enhances the antiviral state of common target cells for viral infection such as respiratory or gastrointestinal epithelium." (PMID 33542718, 2020). "TRIM21 mediates the polyubiquitination and degradation of the DNA sensor DDX41 and the IRF transcription factors IRF3, IRF5, and IRF7 to negatively regulate the production of interferon-β during viral infection." (PMID 33061806, 2020). "This suggest an important role of chicken IRF7 in the regulation of antigen presentation against viral infection through the MHC II family of genes." (PMID 32252379, 2020). "TANK-binding kinase 1 (TBK1) has been reported to be in the upstream of both the IRF7 pathway and the NF-kB pathway in virus infection." (PMID 31941042, 2020).
viral infection (continued). "Viral infection triggers host innate immune responses by activating transcription factors IRF3/IRF7 and NF-κB, which coordinately induce the production of type I IFNs." (PMID 32678830, 2020). "IRF7 was identified as the regulator of the type I IFN response in an Irf7-/- mouse model, in which the Irf7-/- mouse was significantly more vulnerable to viral infections, with markedly inhibited type I IFN expression, than the wild type." (PMID 32252379, 2020). "The MERS-CoV-shared genes KRT6B and TNFAIP3 had a high p-value associated with SARS-CoV-2, whereas genes such as OAS1-3, IRF9, IRF7, STAT1, PML and IFIH1 were highly associated with host responses to viral infections and type I interferon." (PMID 33301474, 2020). "We think that the long-term effect of IRF7 in viral-infection-mediated disease is worthy of future study." (PMID 32121148, 2020). "In contrast, the late inducible expression of IRF-7 in fibroblasts after virus infection was shown to be responsible for a delayed kinetics of type I IFN production." (PMID 32373120, 2020). "Most of these DEGs were associated with the host response to virus infection and type I interferons, while others such as IRF9, PML, IRF7, STAT1 and IFIH1 were related to interferon signaling." (PMID 33301474, 2020). "TRIF has been shown to form a complex with TBK-1, a protein kinase that has been reported to directly phosphorylate IRF-3 and IRF-7 in response to viral infection or TLR3 and TLR4 stimulation based on in vitro kinase assays." (PMID 32373120, 2020). "IFN-regulatory factor gene family encodes multiple transcription factors including IRF1, IRF3 and IRF7, and plays essential roles in host defense against viral infection through regulation of IFN expression." (PMID 32983049, 2020). "In total 20 ISGs were significantly upregulated in the RSV-infected mice compared to the non-infected mice and some of the top 10 upregulated genes, such as Irf7,Cxcl10, Ccl2, and Ccl4, are all ISGs known to be induced in response to viral infections." (PMID 33363532, 2020). "For example, both IRF3 and IRF7 are negatively regulated by SUMOylation following viral infection in order to turn off and limit responses." (PMID 30984161, 2019). "In human fibroblast cell lines viral infection activated IRF7 and consequently upregulated MAP3K8, a kinase inhibiting IRF3 dimer formation and promoting the formation of IRF3-IRF7 heterodimers." (PMID 31178872, 2019). "Here we reported a novel role of IFI204 that specifically inhibits the IRF7-mediated type I interferons response during viral infection." (PMID 31603949, 2019). "Viral infection triggers IRF7 dimerization and translocation into the nucleus, where it binds to the promoter region to activate IFN-β transcription." (PMID 31539404, 2019). "CYLD is a target of miR-526a, a potent IFN-β inducer, and miR-526a upregulation during viral infection is partially mediated by IRF7." (PMID 30619109, 2018). "Virus infections induce specific IRF3 phosphorylation that leads to its dimerization with itself or with IRF7 and forms a complex containing CBP/p300 and other coactivators followed by translocation into the nucleus for the expression of IFN-β." (PMID 30671058, 2018). "Among nine IRFs, IRF1, IRF3, IRF5, and IRF7 play a pivotal role in the induction of IFN gene transcription during viral infection." (PMID 30671058, 2018). "During mammalian viral infections, interferon regulatory factor 7 (IRF7) partners with IRF3 to regulate the type I interferon response." (PMID 30356848, 2018). "We demonstrated that pDCs are sufficient to initiate early control of viral infections, via induction of IRF7-prone signaling." (PMID 29914621, 2018). "IFN-α, controlled primarily by IFN regulatory factor 3 (IRF-3) and IFN regulatory factor (IRF-7), plays a crucial role in host defense processes against viral infection." (PMID 28382020, 2017).
viral infection (continued). "TLR9 activation in pDCs results in the phosphorylation and nuclear translocation of transcription factors IRF3 and IRF7, which induce IFNα/β expression in response to viral infection and DNA sensing." (PMID 28861085, 2017). "Robust type I interferon production by virus infection requires the IRF7-RIG-I amplification loop and the stability of RIG-I via post-translational modification by type I IFN." (PMID 28273165, 2017). "Our results first identified the negative regulation of LGP2 to IRF7 in the promoter activity, mRNA, and protein level in response to dsRNA virus infection in fish cells." (PMID 28396670, 2017). "Cells displayed a marked upregulation of many genes known to be involved in the mammalian response to viral infection, including viperin, Mx1, IRF7, IRF1, and RIG-I with approximately 10% of the genes being uncharacterized transcripts." (PMID 29213275, 2017). "Low basal IFN-α expression has been suggested to set an activation threshold by priming cells to respond more rapidly and robustly to viral infection, in part by regulating IRF7 levels." (PMID 28380049, 2017). "Whereas IRF-7 is activated in response to viral infections and NF-κB, IRF-1 responses are mainly triggered by IFN-γ, although they can also be activated by cytosolic pattern recognition receptors." (PMID 28122985, 2017). "In the resting state cells, IRF3 and IRF7 localize in cytoplasm, whereas poly(I:C) stimulation or virus infection induces their cytoplasmic-nuclear translocation." (PMID 28396670, 2017). "IRF7 mediates the production of cytokines in response to a viral infection and plays an important role in promoting apoptosis of virus-infected tumour cells." (PMID 27966453, 2017). "Phosphorylation of the C-terminal serine (Ser) and threonine (Thr) residues is important for IRF3 and IRF7 activation following viral infection." (PMID 28396670, 2017). "SRS2 group eQTL specificity was also seen for TRIM44, which promotes an enhanced cellular response to viral infection, and DDX24, which encodes a type I interferon-inducible DEAD-box protein RNA-helicase modulating IRF7 activity." (PMID 26917434, 2016). "Active de-repression of the antiviral program is largely dependent on the induction of miR-127, which, upon viral infection, potentially suppresses the expression of Bcl6 and impairs the inhibitory complex at IRF7 loci." (PMID 26728228, 2016). "IRF7 is an amplificatory molecule responding to pattern recognition receptor detection of viral infection, inducing a further cascade of IFNs, and is identified as the master regulator of type I IFN-dependent immune responses." (PMID 27822537, 2016). "Together, our data demonstrated a prominent and specific role of the miR-127/Bcl6/IRF7 loop in the host innate immunity against viral infection." (PMID 26728228, 2016). "Viral infections or TLR (e.g. TLR3) engagement activates IRF7, which initially participates in the transcriptional induction of small amounts of type I IFNs." (PMID 25978633, 2015). "Among them, 22 genes (Gm26130, mt-Ts2, Mgst2, Cyp7a1, Vps45, etc.)were clustered as a hot block next to a block containing Irf7 gene that is the master regulator for the induction of type I interferon during viral infection." (PMID 25902143, 2015). "In mammals, once PRRs recognize a viral infection, a signaling cascade leads to the phosphorylation of IRF7 in the cytosol and to the translocation of IRF7 homodimer or IRF3/7 heterodimer into the nucleolus where they activate the type I IFN pathway." (PMID 26186542, 2015). "In these and other studies, IRF3 was shown to be an important component of the immediate-early response to virus infection, while IRF7 is involved in the late induction phase of IFN expression during viral infection." (PMID 25798928, 2015). "Irf7 or Interferon regulatory factor 7, is a transcriptional factor produced in response to viral infections, and the regulation of Irf7 is strongly controlled because of effects on auto-immunity and cancer." (PMID 26251171, 2015).